PTX3 (pentraxin 3)
Diseases named in the same sentence as PTX3 in open-access papers (continued):
Sharing a sentence is not in itself a finding about the gene and the disease.
lupus nephritis (continued). "In lupus nephritis, PPD inhibits PTX3 overexpression, suppresses mesangial cell proliferation, and improves renal pathology in MRL/lpr mice through blockade of the PTX3/MAPK/ERK1/2 pathway." (PMID 41415561, 2025). "Comparisons of clinical, laboratory, and pathological data between patients with and without anti-PTX3 auto-antibodies in lupus nephritis." (PMID 28393653, 2017). "In conclusion, anti-PTX3 auto-antibodies were less prevalent in active lupus nephritis patients compared with SLE without renal involvement and associated with less severe renal damage, especially with the combined evaluation of serum PTX3 levels." (PMID 28393653, 2017). "recently found that the PTX3 level and the degree of renal fibrosis were both higher in patients without anti-PTX3 auto-antibodies than those positive in lupus nephritis." (PMID 28393653, 2017). "In the current study, we confirmed that anti-PTX3 auto-antibodies were less prevalent in active lupus nephritis patients compared with SLE without renal involvement, which was consistent with the previous study." (PMID 28393653, 2017). "The average level of serum PTX3 in the discovery cohort of lupus nephritis was significantly higher than that in nonrenal involvement SLE group and normal controls (P < 0.001, P < 0.001, respectively), which was confirmed by the validation cohort." (PMID 26817892, 2016). "It indicated that the combination of serum PTX3 level and anti-PTX3 auto-antibodies could predict lupus nephritis activity better, not the whole SLE disease activity as the SLEDAI scores were comparable between the two groups." (PMID 28393653, 2017). "The positive ratio of anti-PTX3 auto-antibodies in SLE without the renal involvement group was significantly higher than that in the lupus nephritis group (40.7% (61/150) versus 19.4% (38/196), p < .001) and healthy controls (40.7% (61/150) versus 2% (2/100), p < .001)." (PMID 28393653, 2017). "The average level of serum PTX3 in active lupus nephritis patients was significantly higher than that in SLE without renal involvement (3.207 (0.399–56.376) ng/ml versus 1.065 (0.040–9.098) ng/ml, p < .001) and normal controls (3.207 (0.399–56.376) ng/ml versus 0.993 (0.007–2.655) ng/ml, p < .001)." (PMID 28393653, 2017). "Experimental animal model further supported that the anti-PTX3 auto-antibodies might exert a protective role against renal immune inflammatory damage, although the detailed descriptions between anti-PTX3 auto-antibodies and its clinical significance in human lupus nephritis was lacked." (PMID 28393653, 2017). "Moreover, in patients with lupus nephritis, a significant correlation was found between serum TNF-α concentration and serum PTX3 level (r = 0.351, P = 0.012), but not between IL-1β and PTX3 (r = 0.062, P = 0.861)." (PMID 26817892, 2016).
migraine (11 papers, 2019 to 2025). "An inflammatory connection to migraine has been alluded to with the observations that serum acute phase proteins pentraxin-3 and fibrinogen are found associated with migraine duration." (PMID 31026304, 2019). "Elevated PTX3 levels, correlated with migraine severity, suggest that ongoing inflammation and endothelial dysfunction contribute to pediatric migraine pathogenesis." (PMID 40149800, 2025). "First, because no prior research has evaluated circulating RvD1 or MaR1 levels in migraine patients, the sample size was estimated using effect size data from PTX3, a distinct inflammatory biomarker." (PMID 41462993, 2025). "PTX-3 serum levels increase during migraine attacks and are higher in the interictal phase in EM patients than in HC." (PMID 36982428, 2023). "Increased levels of C-reactive protein or acute-phase reactant pentraxin 3 (PTX3) were found in the systemic circulation of migraine patients." (PMID 33671172, 2021). "Two studies have demonstrated higher plasma levels of PTX3 in migraine patients during attacks when compared to interictal periods or healthy controls." (PMID 32244987, 2020). "Regarding migraine, only two studies have demonstrated higher plasma levels of PTX3 measured during attacks and compared to interictal periods and control subjects." (PMID 32244987, 2020). "Our current results suggest that PTX3 upregulation in MLV endpoints during migraine may indicate a state of endothelial damage and/or function as a chemoattractant for egressing immune cells." (PMID 38743922, 2024). "In our study, we hypothesized that patients with migraine show increased levels of PTX3 and sTWEAK as a result of altered endothelial function, even in the absence of vascular risk factors." (PMID 32244987, 2020). "Because no prior studies have quantified RvD1 or MaR1 levels in migraine patients, the power analysis relied on effect size estimates derived from PTX3, a different inflammatory biomarker." (PMID 41462993, 2025). "Since longer attacks are associated with lower serum levels of PTX-3, PTX-3 is not an indicator of pain intensity, while it may be correlated with the length of the disease, to suggest that inflammatory processes may change during migraine progression." (PMID 36982428, 2023). "In conclusion, patients with CM had increased circulating levels of PTX3 and sTWEAK as well as diminished FMD compared to subjects without migraine." (PMID 32244987, 2020).
septic shock (11 papers, 2016 to 2024). Shock caused by infection; frequently caused by gram negative bacteria, although some cases have been caused by other bacteria, viruses, fungi, and protozoa; characterized by fever, chills, tachycardia, tachypnea, and hypotension. "In a group of 112 patients admitted to the ICU with septic shock, baseline PTX3 levels were the only independent risk factor for 28-day mortality, in contrast with CRP and PCT." (PMID 31031772, 2019). "In septic shock patients, early high plasma PTX3 predicts subsequent new organ failure, and a smaller subsequent drop in circulating PTX3 over time predicts an increased risk of death." (PMID 30687307, 2018). "High PTX3 level is associated with septic shock, amputation and risk of death in patients with NSTI, but it is not an independent predictor of 180-day mortality in this patient group." (PMID 26880104, 2016). "In a prospective study with 112 patients with septic shock, baseline PTX3 levels were an independent predictor of 28-day mortality, unlike CRP and PCT." (PMID 33301518, 2020). "The univariate analysis determined that the significant risk factors for 28-day mortality were IL-6, PTX3, lactate, SOFA and APACHE II scores, and septic shock." (PMID 31718563, 2019). "From the 46 septic shock patients admitted to our institution, follow-up samples were obtained from 28 patients within 24 h of discharge to measure IL-6 and PTX3, 15 of whom recovered, and 13 died." (PMID 31718563, 2019). "The AUC to discriminate septic shock was 0.80 for IL-6 (95% CI, 0.71–0.89; P < 0.001), 0.70 for PTX3 (95% CI, 0.60–0.81; P < 0.001), 0.73 for PCT (95% CI, 0.63–0.83; P < 0.001), and 0.53 for CRP (95% CI, 0.42–0.65; P = 0.603)." (PMID 31718563, 2019). "For septic shock patients, an overall decrease in induction efficiency was observed for both TNFα and PTX3 at the transcriptional level, the lowest level being reached after 24 h of stimulation, similarly to HV." (PMID 30687307, 2018). "As in septic patients immune alterations have been described, we therefore sought to investigate whether such cells participated in the elevation of PTX3 over the first days after septic shock onset." (PMID 30687307, 2018). "Conversely, septic shock patients did not have altered capacity to secrete PTX3 after LPS stimulation." (PMID 30687307, 2018). "We compared PTX3, procalcitonin and C-reactive protein in septic shock versus nonshock patients and in amputated versus nonamputated patients using the Mann-Whitney U test." (PMID 26880104, 2016).
acute respiratory distress syndrome (10 papers, 2013 to 2024). Progressive and life-threatening pulmonary distress in the absence of an underlying pulmonary condition, usually following major trauma or surgery. "In different models of sterile inflammation, such as pleurisy and acid-induced acute respiratory distress syndrome, PTX3 has been shown to serve as a negative regulator of neutrophil recruitment by interacting with P-selectin, thus limiting tissue injury." (PMID 37222419, 2023). "In ALI and acute respiratory distress syndrome patients, plasma PTX3 is elevated and is positively correlated with lung injury parameters." (PMID 31354697, 2019). "Pentraxin 3 levels are correlated with acute lung injury, acute respiratory distress syndrome severity, and systemic involvement." (PMID 29861799, 2018). "Considering that acute respiratory distress syndrome due to COVID-19 pneumonia develops very aggressively and rapidly, it can be said that measuring serum long PTX-3 levels has been proposed to be a marker for early diagnosis in order to predict the progression of the disease." (PMID 33315349, 2021). "Interestingly, PTX3 is widely accepted as a marker of severity and an outcome predictor in acute lung injury (ALI)/acute respiratory distress syndrome (ARDS) patients." (PMID 26644796, 2015).
Autoimmunity (10 papers, 2011 to 2025). The occurrence of an immune reaction against the organism's own cells or tissues. "The experimental strategy of generating Ptx3-deficient autoimmune B6lpr mice intended to test the role of Ptx3 as a potential modifier gene for established autoimmunity." (PMID 21637713, 2011). "Surprisingly, Ptx3-deficiency only marginally affected systemic autoimmunity in B6lpr mice." (PMID 21637713, 2011). "One of the most intriguing discoveries in autoimmunity are anti-pentraxin-3 (PTX3) antibodies, which have been detected in up to a third of RA patients who do not express ACPA (i.e. seronegative RA)." (PMID 39340807, 2025). "PTX3 is involved in the humoral innate immunity by recognizing microbial moieties and damaged tissues and in regulating inflammation and autoimmunity." (PMID 35204613, 2022). "PTX3 is known to play a dual role in both protecting cells against pathogens and controlling autoimmunity." (PMID 28046107, 2017). "Pentraxin-3 (PTX3) is a component of innate immune system and recently implicated in autoimmunity." (PMID 29675428, 2018). "The functions of PTX3 may include promoting pathogen removal, inhibiting removal of dying cells (controlling autoimmunity), and a dual role (enhancement and reduction) in complement-associated immune responses." (PMID 23383162, 2013). "Hence, present evidences suggest that PTX3 is like a two-edged sword in protecting against autoimmunity and favoring autoimmunity." (PMID 23383162, 2013). "Spleen and kidney PTX3 expression decreased over time when autoimmunity progresses in B6lpr mice." (PMID 21637713, 2011). "Hence, decreased levels of PTX3 could result in accumulation of cell debris and subsequent inflammation and autoimmunity." (PMID 31137925, 2019). "In addition, Ptx3-deficient B6 mice did not reveal any sign of spontaneous autoimmunity, e.g. autoantibodies against ANA, dsDNA or rheumatoid factor up to 12 months of age." (PMID 21637713, 2011). "Thus, PTX3 is increasingly expressed in lungs during the progression of autoimmunity of B6lpr mice." (PMID 21637713, 2011). "Our data now demonstrate that the evolution of autoimmunity and lupus autoantibodies in B6lpr mice seems to be independent of PTX3 but that PTX3 has a non-redundant role in surpressing autoimmune lung injury." (PMID 21637713, 2011). "Thus, PTX3 is redundant for the expansion of B cells and plasma cells as well as for the production of numerous autoantibodies against nuclear autoantigens in B6lpr mice lack of PTX3 alone does not induce autoimmunity against DNA." (PMID 21637713, 2011).
Cirrhosis (10 papers, 2013 to 2025). A chronic disorder of the liver in which liver tissue becomes scarred and is partially replaced by regenerative nodules and fibrotic tissue resulting in loss of liver function. "In relation to cirrhosis, together with gender (OR 5.612, P = 0.041), age (OR 1.061, P = 0.047), HBV DNA (OR 0.619, P = 0.022) and albumin (OR 0.909, P = 0.026), PTX3 (OR 1.671, P < 0.001) was an independent risk factor for HCC." (PMID 33219288, 2020). "The best marker was PTX3 with AUCs = 0.802 for detecting F≥2, AUCs = 0.867 for detecting F≥3, and AUCs = 0.937 for detecting cirrhosis." (PMID 31061822, 2019). "However, other published data show a decreasing PTX3 level in late cirrhosis, demonstrating the need for further studies." (PMID 39519095, 2024). "The discrimination of HCC by PTX3 levels was not influenced by the underlying disease (chronic hepatitis or cirrhosis) or the usage of antiviral treatment with nucleos(t)ide analogues." (PMID 33219288, 2020). "In summary, PTX3 is not of diagnostic value in cirrhosis and HCC patients." (PMID 32078718, 2020). "Sera from HBV-HCC patients were characterized by higher MMP-2 and pentraxin-3 levels, with a trend toward lower cytokine and chemokine concentrations, when compared to HBV patients with cirrhosis." (PMID 36230823, 2022). "Serum from HCV-HCC patients showed higher levels of MMP-2 and pentraxin-3 as well, but, in addition, exhibited increased levels of IL-6 and HGF in HCC compared to HCV-cirrhosis patients." (PMID 36230823, 2022). "PTX3 levels were significantly higher in HBV patients than in healthy controls (P < 0.001) and in HCC than in chronic hepatitis (P < 0.001) or cirrhosis patients (P < 0.001)." (PMID 33219288, 2020). "The study revealed that serum PTX3 levels were significantly higher in patients with chronic HBV infection compared to healthy individuals, and notably elevated in those with HBV-related HCC compared to patients with chronic hepatitis or cirrhosis." (PMID 41462970, 2025). "PTX3 levels were not changed in cirrhosis patients with ascites or varices and did not correlate with the hepatic venous pressure gradient." (PMID 32078718, 2020). "This study demonstrated significantly elevated serum PTX3 levels in patients with chronic HBV infection compared to healthy controls and in patients with HBV-related HCC compared to patients with chronic hepatitis or cirrhosis." (PMID 33219288, 2020). "For diagnostic accuracy, PTX3 exhibited higher AUC, sensitivity, and specificity than did AFP in HCC patients in relation to chronic hepatitis, cirrhosis and chronic HBV infection without HCC." (PMID 33219288, 2020). "In cirrhosis patients, PTX3 was neither related to ascites volume nor to variceal size." (PMID 32078718, 2020). "In particular, PTX3 levels were highly discriminative of AFP-negative (≤ 20 ng/mL) and early-stage HCC from chronic hepatitis, cirrhosis and chronic HBV infection without HCC." (PMID 33219288, 2020). "After PSM, all the parameters (except PTX3 levels) in HCC (n = 44) versus chronic hepatitis (n = 44), HCC (n = 61) versus cirrhosis (n = 61) and HCC (n = 80) versus non-HCC (n = 80) were well matched." (PMID 33219288, 2020). "Notably, serum PTX3 demonstrated strong discriminatory power in distinguishing HCC from chronic hepatitis, cirrhosis, and chronic HBV infection without HCC." (PMID 41462970, 2025). "Importantly, PTX3 levels were especially effective in identifying α-fetoprotein (AFP)-negative and early-stage HCC, distinguishing it from chronic hepatitis, cirrhosis, and chronic HBV infection without HCC." (PMID 41462970, 2025). "The combination of PTX3 with AFP, although slightly increased AUC values, did not significantly increase the performance of PTX3 for discriminating late-stage HCC from chronic hepatitis (AUC 0.965), cirrhosis (AUC 0.944) or chronic HBV infection without HCC (AUC 0.956)." (PMID 33219288, 2020).
Cirrhosis (continued). "Importantly, serum PTX3 levels could highly discriminate HCC from chronic hepatitis, cirrhosis and chronic HBV infection without HCC." (PMID 33219288, 2020). "Therefore, PTX3 levels of the HCC and cirrhosis patients could not be compared." (PMID 32078718, 2020).
diabetic nephropathy (10 papers, 2013 to 2025). "Additionally, it has been observed that the PTX3 level in the kidney tissue is associated with kidney damage in diabetic nephropathy, and PTX3 expression in the kidney is significantly reduced in diabetic nephropathy." (PMID 39697970, 2024). "PTX3 may be associated with kidney damage, but the pathogenesis of PTX3 in diabetic nephropathy is still unclear." (PMID 31780874, 2019). "Moreover, the varied alterations in PTX3 and adropin, as inflammatory markers, indicate their potential to predict renal injury in diabetic patients to differing extents and their association with the development of diabetic kidney disease." (PMID 40332236, 2025). "Therefore, PTX3 is closely related to endothelial cell function and diabetic nephropathy, and PTX3 may play an important role in renal damage caused by endothelial cell dysfunction." (PMID 31780874, 2019). "PTX3, another differentially expressed gene, is a pentraxin 3 gene that is involved in the progression of diabetic complications including diabetic nephropathy and retinopathy by the activation of immunological and inflammatory mechanisms." (PMID 36051390, 2022). "In this study, we evaluated the expression of PTX3 and other related renal injury parameters in the renal tissue of diabetic rats with early diabetic nephropathy." (PMID 29725602, 2018). "Only one study on the association between PTX3 and DN is currently available, which reported that the expression of PTX3 was remarkably decreased in experimental diabetic nephropathy compared with controls." (PMID 29725602, 2018). "PTX3 may also be a potential therapeutic target for the treatment of diabetic nephropathy." (PMID 31780874, 2019). "Conversely, PTX-3, IL-6, and hs-CRP levels were decreased after periodontal treatment only in PD patients with diabetic nephropathy." (PMID 31382656, 2019). "In OVA/Alum model, IL-4 was also shown to increase in PTX3-treated mice, so was IL-13, though not significant, in line with the results observed in animal model of diabetic nephropathy." (PMID 32938460, 2020). "Yet, in animal experiments in mice, Pentraxin-3 infusion attenuated renal damage in diabetic nephropathy, whereas knock-out mice lacking pentraxin-3 showed more vascular inflammation and macrophage accumulation within atherosclerotic plaque." (PMID 29316724, 2018).